CTNNB1 (catenin beta 1)
Diseases named in the same sentence as CTNNB1 in open-access papers (continued):
Sharing a sentence is not in itself a finding about the gene and the disease.
cancer (continued). "It included a number of genes with obvious cancer relevance including CD44, catenin b1 (CTNNB1), vimentin (VIM), cathepsins B and S (CTSB, CTSS), MMP9, XIAP, JunD, numerous proto-oncogenes (REL, YES, SET, FGR, CRK), and HSP90AA1 (which is a chaperone which stabilizes MIF as a client)." (PMID 28957348, 2017). "Furthermore, CTNNB1 knockdown did not affect the TFAP2C expression at the mRNA or protein level in these cancer cells." (PMID 40837414, 2025). "For instance, the depletion of CTNNB1 mutations in HBV-positive HCC cases, a known association, was not highlighted because the p-value for CTNNB1 mutations in the combined cohort of all eligible cancer types did not meet our significance threshold." (PMID 40595559, 2025). "In addition, Wnt pathway alterations were detected in many kinds of cancer, confirming its importance during bladder carcinogenesis; a finding compatible with our results that showed a significant elevation in WNT7A and CTNNB1 expression in high stages." (PMID 36140796, 2022). "CTNNB1 may be primarily translated from the 3′ SP transcripts that are exported to the cytoplasm upon splicing, highlighting the importance of 3′ UTR splicing in driving oncogene expression and cancer progression." (PMID 35618746, 2022). "Next, we investigated whether cancer stem cell markers and function could be manipulated by directly disrupting β-catenin making use of doxycycline (DOX) inducible short-hairpin RNA targeting CTNNB1 (β-catenin) transcripts in 468’R cells (iCTNNB1-KD)." (PMID 34367990, 2021). "Six overexpressed oncogenes including BCL2, NOTCH1, SOX4, and CTNNB1 and 10 downregulated tumor suppressor genes including PRKCB, IRF1, CYLD, and TGFB1 were identified as the targets of the DE miRNAs, which may promote cancer development." (PMID 34336826, 2021). "PIK3CA-mutant cancers displayed higher expression of 12 of the 17 Wnt genes compared to PIK3CA wild-type tumors, including five Wnt target genes (LEF1, MYCN, FZD7, SFRP2, and TNFRSF11B) and seven Wnt signaling components (TCF7L1, TCF7L2, CTNNB1, FZD4, SFRP1, WNT5A, and MSX2)." (PMID 34035258, 2021). "However, the patients with cancer recurrence showed a higher level of CTNNB1 gene expression than those without recurrence." (PMID 32764696, 2020). "NEFH also associated with APC (another WNT pathway member, upstream of CTNNB1), through GSN, in our dataset analysis, Thus, these findings might implicate NEFH in WNT signaling in cancer, even as NEFH’s role in cancer is yet to be discovered." (PMID 31740709, 2019). "However, inhibiting Wnt-CTNNB1 signaling pathway alone is unlikely to succeed in anti-cancer treatment owing to the co-activation of numerous oncogenic pathways in most cancers." (PMID 28831115, 2017). "Interestingly, vimentin and CTNNB1 over-expression and/or cytoplasmic accumulation (as we found in cancer cells expressing high level of MICAL2 in vitro) are both known predictors of hematogenous metastasis in human cancer." (PMID 26689989, 2016). "For example, the gene CTNNB1 has more than 1.5-fold higher expression in the APC mutant cell lines than in the APC wide-type cell lines, raising the possibility that the viability of APC mutant cancer cells might depend on CTNNB1's expression." (PMID 26937901, 2016). "Our results show that the mean of CTNNB1's GPVs in the APC mutant cell lines is 20% of that in the APC wild-type cell lines (P value <10–7), and CTNNB1 has significantly higher level of expression in APC mutant cancer cell lines than in wide-type cell lines (P value = 0.015, fold-change = 1.52)." (PMID 26937901, 2016).
cancer (continued). "For instance, quite recently TRα was found to enhance cancer cell migration and metastasis via inhibition of miR-17 as well as to maintain pro-neoplastic potency by interacting with the cyclin D1/CDK/Rb/E2F cascade, the wnt pathway or by inducing CTNNB1 gene expression." (PMID 26029931, 2015). "In four cases (AKT3, AR, MAPK1, and CTNNB1), we could observe a significant negative correlation in normal tissue, which was either non-significant or was significantly positive in cancer." (PMID 20920310, 2010). "In addition, mutations in CTNNB1 could irregularly activate the WNT pathway without the ligands and subsequently result in the abnormal growth of cells and development of cancer." (PMID 35712679, 2021). "We first evaluated whether in fetal‐like HB cell lines, the partial deletion of CTNNB1 exon 4 could alter the capability of β‐catenin to interact with BCL9 and BCL9L, which are established co‐activators of the Wnt pathway important to specify a stem cell‐like phenotype in cancer cells." (PMID 28923827, 2017). "Finally, we also reviewed PIK3CA, CTNNB1, and ARID1A, as well as KRAS and BRAF, for somatic mutations in these genes have been reported to occur in EOC subtypes and corresponding cell lines most often representing other non-HGS subtype cancers." (PMID 26622941, 2015). "Major improvements that might be hypothesized are (i) lumping together MMRd carcinomas, regardless of grade and histotype (with the exception of SWI/SNF-deficient UEC/DEC) and (ii) substratifying the risk in NSMP EECs based on further prognostic factors (e.g., CTNNB1 mutations)." (PMID 34073635, 2021). "CTNNB1 and SHC1 were amplified (0.3% and 22% of patients, respectively), but were not included in the targeted sequencing performed on 173 cancer-related genes in METABRIC." (PMID 32463822, 2020). "The importance of this remains uncertain and we would note that, unlike CTNNB1, HGC6.3 remains uncharacterized, and is not in the COSMIC Cancer Gene Census (CCGC)." (PMID 33148256, 2020). "These included the well‐studied cases of CTNNB1, PIK3R1, and SMAD4 proteins as well as proteins that are as yet not annotated as drivers, but are functionally connected to cancer pathways." (PMID 29572294, 2018). "We further detected the expression of some reported stemness-related genes in HCC and CRC stem cells including CTNNB1, HES1, SMAD4, GLI1, STAT3 and BMI122, 23, 24, 25 in the cancer cell lines with or without PS341 treatment." (PMID 26915315, 2016). "Unlike CASP8 and CTNNB1, which are part of our CONIM list, SPOP did not pass our pan-cancer CNA enrichment filter criteria because the effect of SPOP on CNAs is highly cancer-type-specific." (PMID 27831464, 2016). "Among genes (RB1, ERBB2, CTNNB1) identified by method CPGA-SMCMN, although they are not enriched in a biological pathway with any other identified genes, they have been reported to be important cancer related genes." (PMID 37221474, 2023). "Apparently, the observation that RNA levels of CTNNB1 and PTMA were higher in HCC than in control healthy liver tissues could not fully explain cancer sensitivity to the drug." (PMID 26517516, 2015).
infection (33 papers, 2011 to 2025). The state of being infected such as from the introduction of a foreign agent such as serum, vaccine, antigenic substance or organism. "CTNNB1-deficient hESC colonies were established by shRNA infection, and the CTNNB1 expression and stem cell characteristics were explored after interference." (PMID 33029148, 2020). "Interestingly, HV-HP infection was also associated with a reduction in CTNNB1 (catenin beta 1), and SNAI1 mRNA expression levels." (PMID 40642068, 2025). "At day 9 post-infection, network 2 illustrated interactions between several miRNAs and genes such as CTNNB1, SMARCA4, and ESR1." (PMID 41157560, 2025). "We found enhanced growth of T. gondii concomitant to higher expression of β-catenin (CTNNB1) mRNA at indicated time of infection." (PMID 30770800, 2019). "Decreased Wnt5a protein and decreased Ctnnb1 mRNA expression in the mouse macrophage cell line RAW264.7 have also been reported upon infection with Pseudomonas (P.)aeruginosa." (PMID 31781093, 2019). "Using site-specific primers, we confirm the consistent and effective Ad-Cre-mediated excision of Ctnnb1 Exon 3 by 48 h post-infection, compared to fibroblasts carrying the same transgene and transduced with Adenovirus GFP." (PMID 29209359, 2017). "Axin2, a well-established direct target of β-catenin, was up-regulated by 40 to 70-fold in cells at 72 h post-infection across all GOF samples further demonstrating successful excision of Ctnnb1 Exon 3 and activation of the pathway." (PMID 29209359, 2017). "IFIT1 and DDX58 proteins increased from 24 to 48 hours post-infection while phosphorylated NFKBIA increased up to 32 hours post-infection in CTNNB1 knockdown cells." (PMID 23785285, 2013). "This is in contrast to the LRRFIP1-dependent phosphorylation of CTNNB1 at Ser552 upon infection with Listeria monocytogenes, which promotes its transcriptional activation required for IFNB1 production in mouse macrophages." (PMID 23785285, 2013). "Following infection, CTNNB1 is detected in the nucleus of SeV-infected HEK 293T cells, similarly to IRF3." (PMID 23785285, 2013). "Importantly, H. pylori infection of AGS cells induced strong upregulation of COL4A1 and CTNNB1 and significantly increased proliferation, clonogenicity, and migration, demonstrating a direct infection-driven oncogenic response." (PMID 41291892, 2025). "The majority of genes (CTNNB1, MARCO, STAT5a/b, TAP1, and TAP2) that regulate proliferation and differentiation of immune cells showed a differential higher expression in KO and SP-A variants in response to infection." (PMID 32670284, 2020). "At very short times after the infection (5 min), a significant increase in the transcription of the gene coding for β-catenin (Ctnnb1) was detected, while the protein expression and translocation to the nucleus began at 2 h pi and reached the maximum between 8 and 12 h pi." (PMID 29743880, 2018). "Indeed, immunoblot analysis of infected cell extracts demonstrated the progressive increase in activated CTNNB1 (dephosphorylated on Ser37 or Thr41) from 4 to 24 hours post-infection, followed by a slight decrease at 48 hours." (PMID 23785285, 2013). "Evidently, clarification of the relationship between infection with a nonintegrating virus and subsequent CTNNB1 mutations may prove exceedingly useful for the design of strategies aimed at preventing HCV-associated HCC." (PMID 28035485, 2017). "In particular, we validated CTNNB1 S552 and p38 (MAPK11-14) T180/Y182 phosphorylation as well as CTNNB1 and p38 protein abundance dynamics upon MPXV infection." (PMID 39117661, 2024). "Treatment with 2-pyridone PIM1 inhibitor was able to significantly downregulate Notch1, Notch2, CTNNB1, and CDC42 in SARS-CoV-2-infected cells at 24 h post-infection (p-value < 0.001)." (PMID 37211584, 2023).
infection (continued). "SARS-CoV-2 infection resulted in a significant overexpression of Notch1, Notch2, CTNNB1, CDC42, and PSEN1 after 24 h of infection." (PMID 37211584, 2023). "We found in the qRT-PCR analysis that CTNNB1 mRNA expression was significantly inhibited by miR-320a mimics and promoted by miR-320a inhibitor, while DANCR expression remained unchanged upon infection." (PMID 32778797, 2020). "First, three FLAG-tagged armadillo repeat-containing proteins, PKP2, PKP4 (a.k.a. p0071) and β-catenin (also known as CTNNB1) were transfected into HEK293 cells, followed by infection with the PR8-Gluc." (PMID 28169297, 2017). "However, in response to infection, male mice exhibited higher expression levels of CDKN1B, and CTNNB1 (KO, 1A3), TCF4 (1A0, 6A2), TAP1, and TAP2, (1A0), CDKN1A, (1A3, 6A2), MARCO, and MMP12 (1A3), CCND1, CDK2, IRF and MYC (6A2) compared to females." (PMID 32670284, 2020). "Likewise, the Trefoil Factor Initiated Mucosal Healing pathways were significantly suppressed in early stage of infection, more specifically, PTK2, GHR, RHOA, CTNNB1, MAPK3, and SHC1 genes." (PMID 24349118, 2013). "Of the 227 BRD4 interactors that were recruited to the BRD4 complex during RSV-infection, we observe that 95 ( 42%) are disrupted to some degree by treatment with ZL0454, including most of the transcription factors described in the earlier section (e.g., c-JUN, CTNNB1, JUP, DDX3X, MTDH)." (PMID 33799525, 2021). "Knock-down of WNT2 and WNT3 (but not WNT1, CTNNB1, or LEF1) impaired infection of HeLa cells by Dengue virus." (PMID 31781093, 2019). "However, our screening also identified invasion- and migration-related genes that were not significantly modulated upon infection (i.e., PAPPA, SNAIL, MMP9, MMP11, ICAM1, CTNNB1, and CDH2)." (PMID 41450565, 2025).
neurodevelopmental disorder (23 papers, 2016 to 2026). A behavioral and cognitive disorder with onset during the developmental period that involves impaired or aberrant development of intellectual, motor, or social functions. "Our findings place CTNND2 alongside other WNT-regulating genes such as APC, CHD8, and CTNNB1, whose disruption similarly causes variable neurodevelopmental disorders." (PMID 41502569, 2025). "Assessment of the novel CTNNB1 variant suggested that it is a likely pathogenic one and raised the diagnosis of CTNNB1 neurodevelopmental disorder (OMIM 615,075)." (PMID 38225558, 2024). "• CTNNB1 neurodevelopmental disorder develops as a consequence of de novo germline loss-of-function pathogenic variants of the catenin beta-1 (CTNNB1) gene." (PMID 38225558, 2024). "Here, we present the case of a Hungarian patient affected by CTNNB1 neurodevelopmental disorder with a novel likely pathogenic frameshift variant p.Ala636SerfsTer12 in the CTNNB1 gene." (PMID 38225558, 2024). "In this study, we identified a novel variant in the clinically and genetically homogenous CTNNB1 neurodevelopmental disorder." (PMID 38225558, 2024). "Loss-of-function mutations of CTNNB1 have been established as the cause of neurodevelopmental disorder with spastic diplegia and visual defects." (PMID 35935366, 2022). "Neurodevelopmental disorder patients with de novo loss-of-function mutations in CTNNB1 (NM_001904.4)." (PMID 35935366, 2022). "Although we searched for other modifying factors determining clinical manifestations of CTNNB1-related neurodevelopmental disorder, such as mutation type and location, gender was the only significant factor associated with autistic features in our analysis." (PMID 35935366, 2022). "Here, we report seven new cases of CTNNB1‐related neurodevelopmental disorder, all harboring de novo variants, six of which were previously unreported." (PMID 33350591, 2021). "De novo mutations of CTNNB1 have been found in CHD cases that also present neurodevelopmental disorders." (PMID 28228731, 2017). "Mutations in CTNNB1 (chr3: 41,194,837-41,260,096) are responsible for a wide spectrum of neurodevelopmental disorders." (PMID 26968164, 2016). "We found that CTNNB1 mutation can cause neurodevelopmental disorder, which could be accompanied by retinal detachment and polydactyly." (PMID 33425807, 2020). "Notably, recent findings indicate that CTNNB1 and its various polymorphisms may play a significant role in neurodevelopmental disorders by disrupting the Wnt signaling pathway, thereby affecting synaptic plasticity, apoptosis, and neurogenesis." (PMID 40690007, 2026). "We describe a Hungarian patient affected by a CTNNB1 neurodevelopmental disorder, which developed as a consequence of a newly identified, de novo frameshift variant in the CTNNB1 gene (c.1902dupG, p.Ala636SerfsTer12)." (PMID 38225558, 2024). "Hopefully, in the near future, these genetic discoveries will completely define the genetic background of the CTNNB1 neurodevelopmental disorder and provide a solid basis for studies developing novel therapeutic modalities for patients." (PMID 38225558, 2024). "Concerning the less frequent symptoms of the CTNNB1 neurodevelopmental disorder related phenotype, the reported Hungarian patient has partial pituitary dysfunction and as a consequence he underwent growth hormone administration." (PMID 38225558, 2024). "In particular, CTNNB1-related neurodevelopmental disorders have various phenotypes, and a genotype-phenotype relationship has not been established." (PMID 37416820, 2023).